LEP (leptin)
Diseases named in the same sentence as LEP in open-access papers (continued):
Sharing a sentence is not in itself a finding about the gene and the disease.
Obesity (continued). "Adipocytes also produce excessive inflammatory cytokines such as tumor necrosis factor-alpha (TNF-a), interleukin 6 (IL6), leptin, and visfatin, which are associated with obesity, IR, or CVD." (PMID 38256617, 2024). "The reduction in leptin levels is particularly relevant, as elevated leptin levels are linked to leptin resistance, a condition commonly observed in obesity and MASLD, which further exacerbates systemic inflammation and insulin resistance." (PMID 39770882, 2024). "Leptin is increased in obesity, and one of the major risk factors for obesity is leptin resistance, which leads to a decrease in satiety caused by disruption of signalling pathways of leptin." (PMID 38546831, 2024). "Mice homozygous for this mutation are leptin-deficient and develop obesity, which appears around 4–5 weeks of age." (PMID 39337328, 2024). "This phenomenon is caused by the decreased hypothalamus responsiveness to leptin in obese patients, namely “obesity-induced leptin resistance”32,33." (PMID 38561362, 2024). "The investigation of combinations involving GLP-1, gastric inhibitory polypeptide (GIP), islet amyloid polypeptide, glucagon, and leptin has revealed their potential to enhance weight loss in adults with obesity and type 2 diabetes." (PMID 39065679, 2024). "Weight loss through restrictive diets and lifestyle modifications has been shown to improve leptin sensitivity, aiding in sustained weight management and reducing the risk of obesity-related comorbidities, including CVD." (PMID 39682585, 2024). "The interplay of adiponectin and leptin in serum is closely related to the development of obesity or obesity-related disorders but appears to have minimal association with adipose tissue." (PMID 39474247, 2024). "Biallelic pathogenic leptin gene variants cause severe early-onset obesity usually associated with low or undetectable circulating leptin levels." (PMID 38470203, 2024). "For these reasons, ASCs are key regulators of obesity-associated sequelae and disease due in part to their control of leptin signaling." (PMID 39439572, 2024). "Elevated leptin levels play a pivotal role in driving obesity and associated metabolic disturbances." (PMID 39335491, 2024). "Supporting these possibilities, our previous studies showed that weight loss improved adipokines such as adiponectin and leptin in patients with obesity." (PMID 38601201, 2024). "In humans, a higher leptin/ghrelin ratio is associated with overweight and obesity, high body mass index and diabetes, regaining of weight after weight loss in overweight/obese patients, and intrapancreatic fat deposition (in the fasted state)." (PMID 39057696, 2024). "Accordingly, the vicious cycle of physical inactivity associatedwith obesity-caused leptin resistance exacerbates a large populationof individuals with obesity and disease-associated burdens." (PMID 38659208, 2024). "We have refined this system into a medium-throughput assay for examining the pathophysiology of a range of obesity-associated LEP variants." (PMID 39002670, 2024). "Thirdly, deficiency of the GH/IGF-1 system produces leptin resistance, which leads to bulimia, obesity and subsequent insulin resistance, all of which contribute to early and aggressive hepatic steatosis." (PMID 38370349, 2024). "ITGA4 was also related to allergic rhinitis associated with obesity, potentially due to its relevance on the leptin–osteopontin interaction in TH2 cells." (PMID 39409176, 2024). "Both central and peripheral leptin have the favorable effect of reducing ectopic fat deposition, which is helpful in illnesses linked to obesity." (PMID 39125635, 2024). "Nonetheless, while anti-angiogenic therapies are effective in many cancers, their effectiveness is likely modulated by obesity-associated signaling, such as through the leptin signaling axis." (PMID 39439572, 2024).
Obesity (continued). "BKS-db/db leptin-deficient mice with spontaneous hyperglycemia, insulin resistance, and obesity symptoms are ideal models for studying type II diabetes and its complications." (PMID 39211388, 2024). "Because higher leptin levels are associated with increased inflammation and cardiovascular risk, leptin is considered a primary factor in MetS, obesity, and cardiovascular disease." (PMID 39139641, 2024). "In another study, comparing leptin-deficient ob/ob mice to controls, a decrease in polyunsaturated lipids and an increase in saturated lipids were measured in this obesity-only model excluding dietary impact." (PMID 38745337, 2024). "Adiponectin and leptin are specific to adipose tissue and are linked to obesity and insulin resistance." (PMID 38674828, 2024). "Obesity can result from altered gene expression or the regulation of parathyroid hormone, calcium, and leptin levels due to vitamin D deficiency." (PMID 39100945, 2024). "Clinically, in people with obesity, increased leptin levels are associated with leptin resistance, resulting in a decrease in the appetite-suppressing effects of leptin." (PMID 38933888, 2024). "Understanding the molecular mechanisms underlying leptin resistance is crucial for the effective application of leptin in obesity treatment." (PMID 38397015, 2024). "Exposure of neonates to MSG severely damages the hypothalamic nuclei which in turn disrupts the hypothalamic signalling cascade of leptin action causing leptin resistance and ultimately leading to overweight/obesity." (PMID 39698791, 2024). "The variants selected were linked to low serum leptin (p.L72S, p.N103K, p.R105W, p.C117Y, and p.P23R) and/or those associated with obesity with a less clear or debated mechanism-of-action (p.H118L, p.S141C, p.D100N)." (PMID 39002670, 2024). "Obesity can cause inhibitory signals to be blunted by leptin resistance, and can result in hyperphagia despite elevated circulating leptin levels." (PMID 38145995, 2024). "Another possible mechanism linking obesity to AD is leptin resistance, a hallmark feature of obesity." (PMID 38290839, 2024). "Although age and genetics are well-established risk factors in AD pathogenesis, the link between leptin resistance, obesity, and the development of AD has been the subject of several studies." (PMID 38933275, 2024). "In a previous meta-analysis, short sleep duration was related to elevated obesity risk, as it is plausible that short sleep duration diminishes leptin hormone levels and increases ghrelin hormone levels." (PMID 39599735, 2024). "Elevated leptin level (hyperleptinemia) not only promotes obesity-associated inflammation, but also potentiates tumor growth, invasion and metastasis." (PMID 39253073, 2024). "Patients with HyOb have classically been described as hyperphagic, and this is supported by the phenotype demonstrated in the majority of the monogenic obesity syndromes involving mutations of genes participating in the leptin/POMC/CART/MCR signaling pathway." (PMID 38019584, 2024). "Many studies have been conducted on the relationship between LEP variants and obesity, one of the most studied variant being LEP rs7799039." (PMID 39203789, 2024). "Chronic central leptin overexpression induces leptin resistance, mimicking many characteristics associated with diet-induced or adult-onset obesity, such as reduced leptin receptors, diminished signaling, and impaired responsiveness to exogenous leptin." (PMID 39203886, 2024). "Regarding the association of leptin with higher risk of excessive GWG, studies found a stronger association of leptin in the second trimester with excessive GWG in women living with overweight or obesity." (PMID 38999894, 2024). "Sleep disturbances have been linked to hypertension, stroke, and obesity via increased ghrelin and decreased leptin levels, impaired glucose tolerance, anxiety and depression, increased evening cortisol production, and higher inflammatory markers." (PMID 38633603, 2024).
Obesity (continued). "In order to investigate how obesity induces chemoresistance of tumor cells, we performed allograft tumor formation assays in wild‐type (WT) and genetic leptin‐deficient ob/ob mice using syngeneic B16F10 melanoma cells." (PMID 38145969, 2024). "While various syndromes are linked to obesity, the literature also highlights several monogenic forms, with the most common resulting from pathogenic variants in the leptin–melanocortin pathway." (PMID 39041042, 2024). "In this study, we investigated how variable susceptibility to obesity in mice affects ovarian steroidogenesis, with a particular focus on the leptin-mediated dysregulation of Nodal signalling pathway in theca cells (TC)." (PMID 39536822, 2024). "One plausible explanation for this association is that obesity induces systemic inflammation and compromises immune response through modulation of leptin secretion, which is known to correlate with PD-1 expression in CD8+ T cells." (PMID 38774877, 2024). "Mutations leading to a reduced or loss of function in genes of the leptin-melanocortin system confer a risk for monogenic forms of obesity." (PMID 38528040, 2024). "An adipocyte-derived satiety factor was identified by the Jeffrey Friedman research group using obese (ob/ob) mice in which the obesity is caused by a mutation in the leptin gene, resulting in complete leptin deficiency." (PMID 38256208, 2024). "Resistance to the central actions of leptin or insulin is linked to increases in obesity and diabetes." (PMID 39590343, 2024). "Obesity is associated with hyperleptinemia, and leptin is a well-established driver of metastasis in breast cancer." (PMID 39439572, 2024). "The positive correlation observed between serum leptin levels and body mass index (BMI) highlights the prevalence of leptin resistance in obese individuals, representing a significant pathogenic mechanism in obesity." (PMID 38623207, 2024). "Disruption at various levels of the leptin–melanocortin pathway or downstream signalling by gene mutations can result in obesity." (PMID 39526054, 2024). "Based on the research results of obesity and hypothyroidism, the association between hypothyroidism and metabolic syndrome, insulin resistance, and leptin will also receive attention." (PMID 38181287, 2024). "Recent theories suggest that resistance to leptin, caused by excess fat, is the first step toward metabolic changes in obesity, leading to insulin resistance." (PMID 39768291, 2024). "The expression and action of leptin are altered in metabolic disorders associated with insulin resistance, such as obesity and gestational diabetes mellitus." (PMID 39683415, 2024). "Obesity is associated with high levels of the proinflammatory adipokine leptin and low levels of the anti-inflammatory adipokine adiponectin, while the reverse (lower leptin and higher adiponectin) is seen in caloric restriction and starvation." (PMID 38887632, 2024). "Leptin analogs, such as metreleptin, are employed in the treatment of congenital leptin deficiency and/or obesity." (PMID 38397015, 2024). "Given the increasing prevalence of obesity and its associated cognitive impairments, early interventions targeting leptin resistance are essential." (PMID 39594988, 2024). "Overall, obesity-associated endocrine deregulation marked by alterations in adiponectin, leptin, insulin, IGF1 and estrogens contributes to increased risk of cancer progression and recurrence in obese breast cancer patients." (PMID 39253073, 2024). "The mechanisms of association between H. pylori and obesity are varied, involving gastrointestinal hormones such as ghrelin and leptin, pivotal in metabolic regulation and energy balance." (PMID 38553516, 2024). "Hyperleptinemia and leptin resistance are closely associated with obesity and T2D, and lower leptin concentrations in circulation are correlated positively with improved insulin sensitivity, lipid metabolism, lower adiposity, and inflammation." (PMID 38610754, 2024).
Obesity (continued). "In patients with obesity, the presence of high circulating levels of leptin, deemed hyperleptinemia, is associated with IR." (PMID 38206766, 2024). "This appears to be a direct mechanism that explains the association between obesity and male infertility since leptin can interfere with the metabolic support of spermatogenesis by SCs." (PMID 38961093, 2024). "According to previous study, obesity increases the crosstalk between chondrocytes and synovial fibroblasts by elevating levels of the pro-inflammatory adipokine leptin, which causes OA patients to produce more IL-6." (PMID 37608129, 2024). "Homozygous loss-of-function mutations in the leptin gene (LEP) cause hyperphagia and severe obesity, primarily through alterations in leptin's affinity for its receptor or changes in serum leptin concentrations." (PMID 39002670, 2024). "For instance, obesity is associated with increased secretion of interleukin 6 (IL-6) and leptin and reduced secretion of adiponectin from AT." (PMID 39408921, 2024). "Leptin, primarily produced by adipose tissue, regulates eating behavior and body weight, and is associated not only with obesity but also with depression." (PMID 39335507, 2024). "The leptin protein has long been associated with obesity phenotypes due to its role in long-term energy homeostasis and atherogenesis." (PMID 39452073, 2024). "Adipocyte- and ASC-derived leptin regulates energy balance, metabolism, endocrine signal regulation and immunity, and increased circulating leptin levels are associated with obesity and its associated sequelae." (PMID 39439572, 2024). "Clinical evidence indicates that patients with severe obesity have a poor curative effect in losing weight if they suffer from leptin or its receptor deficiency, but the underlying mechanism remains elusive." (PMID 38302999, 2024). "Higher circulating levels of leptin have been previously associated with obesity and type 2 diabetes, where neuroendocrine leptin resistance inhibits the ability of leptin to modulate food intake and body weight." (PMID 38035802, 2024). "Disturbance of this leptin-melanocortin pathway explains the susceptibility to develop obesity in individuals with CHUJANS." (PMID 38787418, 2024). "Loss of functional leptin in mice leads to obesity and T2D, driven by hyperphagia and a reduction in energy expenditure." (PMID 38314646, 2024). "Studies on leptin-deficient mice show a dysbiosis of the intestinal microbiome that is comparable to obesity caused by a high-fat diet." (PMID 38397726, 2024). "A pivotal moment in obesity genetics ensued with the identification of mutations in LEP among severely obese children, subsequently expanding to the discovery of mutations in other related genes." (PMID 39041042, 2024). "Research on how physical exercise affects serum leptin levels in children with obesity is relatively scarce compared to similar studies in adults, despite the fact that changes in leptin expression are associated with severe obesity." (PMID 39768291, 2024). "In fact, it is now understood that an overabundance of circulating leptin, secreted by increased AT mass, is a hallmark of obesity." (PMID 38206766, 2024). "In one study, normotension was observed in children with severe obesity and a leptin gene mutation, and in these children, SNS activity was actually decreased." (PMID 39217385, 2024). "Chemerin and RBP4 are associated with obesity and metabolic syndrome markers such as BMI, body fat, leptin, lipid profile, blood glucose measurements, and fatty liver." (PMID 38892481, 2024). "High leptin and decreased adiponectin levels, respectively, are associated with obesity, insulin resistance, T2DM, and CVDs." (PMID 38255954, 2024). "Reduced levels of adiponectin are associated with IR and inflammation, while high levels of leptin reflect obesity and promote inflammation." (PMID 39728125, 2024).
Obesity (continued). "Leptin, an adipokine associated with obesity, was found to be a significant predictor of HF in men without pre-existing CHD, independent from BMI and other mediators, with an adjusted HR of 1.30 per 1-SD increase (p = 0.01)." (PMID 39682585, 2024). "Obesity-associated cytokine, leptin, is known to promote pro-inflammatory cytokine release from immune cells, including macrophages and T-cells." (PMID 39902293, 2024). "Metreleptin, being a leptin analogue administered once-daily subcutaneously, is used in the treatment of obesity in patients with congenital leptin deficiency or congenital/acquired lipodystrophy." (PMID 39125772, 2024). "The rs1137101 (A > G) polymorphism of the LEPR gene was associated with obesity, high leptin level due to disruption of LEPR signaling and greater waist circumferences." (PMID 39203789, 2024). "Though leptin deficiency drives obesity in ob/ob mice through hyperphagia, it is more often leptin resistance through chronic exposure to high circulating leptin, derived from adipose tissue, that promotes pathology in human." (PMID 38314646, 2024). "Obesity, a chronic inflammatory condition, is characterized by increased levels of leptin in the blood, which is associated with complications." (PMID 39768256, 2024). "It is well known that overweight/obesity and/or increased adiposity are associated with elevated serum leptin due to increased adipocyte secretion and leptin resistance." (PMID 38668349, 2024). "This intricate interplay highlights the complexities associated with the role of leptin in obesity and its impact on metabolic regulation." (PMID 38397015, 2024). "Daily subcutaneous injections of recombinant human leptin have been used to treat congenital leptin deficiency-linked obesity." (PMID 39125923, 2024). "Several studies have investigated associations of leptin levels with metabolic complications and have shown that obesity-associated hyperleptinemia promotes hypertension, contributing to increased CVD risk." (PMID 38474344, 2024). "The most frequently studied polymorphism in the LEP gene is rs7799039 (G > A), which is correlated with increased caloric intake, higher BMI, larger waist circumferences, and a heightened risk of obesity." (PMID 39203789, 2024). "Leptin, as an obesity-associated hormone present in co-cultured CMs, can reduce TNF-α levels through positive feedback." (PMID 39072314, 2024). "Leptin, a 16 kDa protein encoded by the obesity gene (ob), was discovered in 1994 and plays a crucial role in the regulation of weight and energy homeostasis." (PMID 38397015, 2024). "MAPK1 has been linked to leptin-resistant obesity and obesity-related precocious puberty and is considered a potential therapeutic target for obesity." (PMID 39484291, 2024). "It has been found that mutation of the LEP gene, the gene responsible for encoding the leptin hormone, is related to elevated fat mass and obesity." (PMID 38892018, 2024). "For instance, leptin, which is primarily produced by adipose tissue, is elevated in individuals with obesity and has been associated with an increased risk of various cancers, including PCa." (PMID 39524226, 2024). "In total, we found 28 distinct homozygous LEP gene variants in patients with severe obesity through our systemic assessment of the published literature." (PMID 38470203, 2024). "In the context of obesity, elevated leptin levels are frequently associated with leptin resistance, a condition marked by the inability to respond to the anorexigenic effects of this hormone." (PMID 39558137, 2024). "Monogenic obesity causes impaired weight regulation in the hypothalamus due to defects in the leptin–melanocortin signalling pathway." (PMID 39526054, 2024). "Increases of leptin, resistin, and visfatin as well as decreases of adiponectin/leptin ratio accompany the expansion and/or the dysfunction of adipose tissue, and have been associated with a multitude of adverse obesity-related outcomes." (PMID 38159164, 2024).